ENSG00000261584 (novel transcript)
Gene: Long non-coding RNA gene on chromosome 6 (26,686,241 to 26,687,964, forward strand). Ensembl gene ENSG00000261584.
Gene Ontology:
Molecular function: triplet codon-amino acid adaptor activity
Biological process: translation